DHCR7 (7-dehydrocholesterol reductase)
Diseases named in the same sentence as DHCR7 in open-access papers (continued):
Sharing a sentence is not in itself a finding about the gene and the disease.
serous ovarian cancer (1 paper, 2026). "Importantly, this metabolic phenotype was independent of molecular subtype, supporting the view that blocking cholesterol biosynthesis, possibly via the upregulated enzymes DHCR7 or DHCR24, could be a promising therapeutic strategy for high-grade serous ovarian cancer." (PMID 41233595, 2026).
squamous cell carcinoma (1 paper, 2022). A carcinoma arising from squamous epithelial cells. "In squamous cell carcinoma subgroup, patients with high DHCR7 expression showed obviously worse OS (P = 0.025), PFI (P = 0.019), and DSS (P = 0.011)." (PMID 36164611, 2022).
steatosis (1 paper, 2025). Increased lipid within the cytoplasm of cells. "Our data suggest that partial ablation of the Dhcr7 gene was sufficient to attenuate the development of MetALD-induced steatosis and tumorigenesis in Dhcr7+/– mice." (PMID 40529212, 2025). "•Partial genetic ablation or pharmacological inhibition of DHCR7 reduced steatosis, inflammation, fibrosis, and HCC development in mice." (PMID 40529212, 2025). "Despite similar cholesterol levels, HFD + EtOH-fed Dhcr7+/– mice were protected from tumorigenesis, steatosis, fibrosis, and inflammation." (PMID 40529212, 2025). "We hypothesized that partial deletion of the Dhcr7 gene would inhibit alcohol-induced steatosis, inflammation, fibrosis, and HCC in DEN/HFD + EtOH-fed Dhcr7+/– mice vs. WT mice treated under the same conditions." (PMID 40529212, 2025).
Stroke (1 paper, 2013). Sudden impairment of blood flow to a part of the brain due to occlusion or rupture of an artery to the brain. "Whilst lower cholesterol levels arising from reduced DHCR7 activity may be advantageous in reducing the risk of heart disease and stroke, these effects are seen in later life and hence less likely to be a selective force in evolution." (PMID 23837623, 2013).
urogenital cancers (1 paper, 2025). "Interestingly, urogenital cancers exhibited varying levels of gene expression depending on the specific type of DHCR7 gene alteration." (PMID 41198144, 2025).
cancer (31 papers, 2015 to 2026). A tumor composed of atypical neoplastic, often pleomorphic cells that invade other tissues. "Our findings revealed that DHCR7 is highly expressed in most cancers, and elevated DHCR7 expression is associated with poor prognosis." (PMID 41198144, 2025). "To further evaluate the diagnostic potential of DHCR7 expression in cancer, we performed receiver operating characteristic (ROC) curve analysis in BLCA, CESC, HNSC, and LIHC." (PMID 41198144, 2025). "In summary, elevated expression of DHCR7 is significantly associated with advanced tumor stage, metastasis, and unfavorable prognosis across multiple human cancer types." (PMID 41198144, 2025). "This study systematically investigated the association between DHCR7 expression and oncogenic processes across multiple cancer types." (PMID 41198144, 2025). "We found that DHCR7 rs12785878 SNP was significantly related to cancer risk in the whole population, Caucasian subgroup, and hospital-based (HB) subgroup." (PMID 34093899, 2021). "Collectively, these results indicate that highly expressed DHCR7 is associated with poor prognosis and might be a potential diagnostic biomarker in most human cancers." (PMID 41198144, 2025). "The enzymes DHCR7 and CYP2R1 play critical roles in the metabolism of vitamin D.25Vitamin D may have a role in cancer risk due to its relationship with DHCR7 and CYP2R1 gene polymorphisms, which is why scientists are looking into this." (PMID 38967113, 2024). "In the field of cancer research, DHCR7 expression levels were found to be positively correlated with the infiltration of cancer-associated fibroblasts (CAFs) and myeloid-derived suppressor cells (MDSCs), and negatively correlated with anti-tumor immune cells in a majority of tumors." (PMID 37759721, 2023). "Moreover, DHCR7 has been assumed to be a correlated gene for vitamin D concentration and carcinoma risk." (PMID 34093899, 2021). "In particular, there is evidence that the DHCR7 enzyme regulates the switch between cholesterol and vitamin D production and that cholesterol metabolism may also be implicated in cancer development." (PMID 31357732, 2019). "Our study is the first to report an association of DHCR7 rs12785878 with any form of cancer." (PMID 31357732, 2019). "In cancer, DHCR7 inhibition elevates 7‐DHC, suppressing ferroptosis but paradoxically promoting metastasis, while targeting upstream enzymes (e.g., EBP) to deplete 7‐DHC induces ferroptosis and inhibits tumor growth." (PMID 41198144, 2025). "We next explored the DHCR7 expression on immune and molecular subtypes among human cancers by the TISIDB database." (PMID 41198144, 2025). "Consistently, the GEPIA database displayed significant elevation of DHCR7 mRNA expression across most cancer types." (PMID 41198144, 2025). "Both genetic deficiency and pharmacological inhibition of DHCR7 (the enzyme that converts 7-DHC to cholesterol) lead to 7-DHC accumulation, conferring robust resistance to ferroptosis in cancer cells and promoting more aggressive tumor phenotypes in vivo." (PMID 40919170, 2025). "Enhancing 7-DHC levels by inhibiting DHCR7 has shown potential for managing cancer metastasis and reducing the progression of kidney IRI." (PMID 39958433, 2025). "Given the high expression of DHCR7 in many cancer cells, it is important to examine its relationship with OS or disease‐free survival (DFS)." (PMID 41198144, 2025). "In this study, we systematically investigated the expression patterns and prognostic significance of DHCR7 across multiple cancer types using diverse datasets." (PMID 41198144, 2025). "Firstly, we analyzed DHCR7 expression in cancer and normal tissues using the Oncomine, TIMER, GEPIA, and UALCAN databases." (PMID 41198144, 2025).
cancer (continued). "Paradoxically, DHCR7 deficiency also confers resistance to ferroptosis via 7‐DHC accumulation, revealing a survival advantage in certain cancers." (PMID 41198144, 2025). "To explore the potential mechanisms, we evaluated DHCR7 expression in immune subtypes and molecular subtypes across various cancers." (PMID 41198144, 2025). "Collectively, our study bridges a critical knowledge gap by presenting the first pan‐cancer, immune‐centric exploration of DHCR7, unveiling its dual function as a metabolic regulator and immunomodulator with potential therapeutic implications." (PMID 41198144, 2025). "These pan‐cancer analyses identify DHCR7 as a multifaceted biomarker with dual prognostic and immunotherapeutic relevance." (PMID 41198144, 2025). "Collectively, these findings indicate that DHCR7 experiences genomic alterations and differential expression in diverse tumor types, underscoring its pivotal role in cancer onset and progression." (PMID 41198144, 2025). "7-dehydrocholesterol reductase (DHCR7) is a key enzyme of cholesterol biosynthesis involved in many cancers, and in this paper, we investigate the effects of DHCR7 on the proliferation and mitochondrial function of BC." (PMID 38526324, 2024). "To obtain a more comprehensive evaluation of DHCR7 expression in cancer, we compared DHCR7 mRNA expression in the TCGA pan-cancer cohort which included 33 types of cancers." (PMID 36164611, 2022). "Data analysis showed that DHCR7 expression was elevated in 27 types of cancer types in comparison with normal samples." (PMID 36164611, 2022). "Our aim is to explore the association of DHCR7 and CYP2R1 SNPs with cancer risk, supplying clues to researchers for screening novel cancer biomarkers." (PMID 34093899, 2021). "First and foremost, association studies of DHCR7 and CYP2R1 polymorphisms with cancer predisposition remain limited." (PMID 34093899, 2021). "Pathogenic or likely pathogenic variants in cancer-associated genes were identified in 37 (6.8%), most frequently in MITF, DICER1, and BRCA2, while 43 (7.9%) harbored variants in NDD-related genes, including DHCR7, POLG, and ARSA." (PMID 41844650, 2026). "To investigate whether this phenomenon extends beyond BLCA, we analyzed other tumors and found that DHCR7 was highly expressed in cisplatin-resistant groups across various cancers." (PMID 40735323, 2025). "Furthermore, DHCR7 expression was positively correlated with advanced tumor stages and metastasis in pan‐cancer samples, including BLCA, KICH, KIRP, LUAD, LUSC, and TGCT." (PMID 41198144, 2025). "Given that cholesterol and its derivatives (e.g., oxysterols) are crucial for membrane integrity, signaling pathways, and post‐translational modifications (e.g., Hedgehog protein maturation), dysregulation of DHCR7 contributes to cancer development through multiple mechanisms." (PMID 41198144, 2025). "The results demonstrated a robust correlation between DHCR7 expression and various immune cell types in human cancers, including T‐cells, CD8 T‐cells, cytotoxic lymphocytes, B‐lineage cells, NK‐cells, monocytic lineage cells, myeloid dendritic cells, neutrophils, endothelial cells, and fibroblasts." (PMID 41198144, 2025). "Overall, these results suggested that DHCR7 is overexpressed in most human cancer tissues." (PMID 41198144, 2025). "Additionally, the UALCAN database analysis indicated significant differential expression of DHCR7 between tumors and healthy tissues in various human cancers." (PMID 41198144, 2025). "Similarly, we found that higher DHCR7 expression was related to poor prognosis in human cancers from the TISIDB database." (PMID 41198144, 2025). "DHCR7 is also considered to be a vitamin D-related gene which may have an influence on calcium homeostasis, bone health, and various cancers." (PMID 36164611, 2022). "We found that DHCR7 was differentially expressed between cancer and normal tissues." (PMID 36164611, 2022).
cancer (continued). "Thus, accumulating researchers are concerned with the correlation between polymorphisms of DHCR7 and CYP2R1 genes and cancer susceptibility." (PMID 34093899, 2021). "Integrating a large-scale pan-cancer study comparing 1739 cell lines of different tumor origins confirmed high DHCR24 and DHCR7 mRNA levels in HGSOC (Fig. EV6C,D)." (PMID 41233595, 2026). "Among 60 ICP genes, including 24 immune inhibitors (such as CTLA4, LAG3, or VEGFB) and 36 activators (TNFRSF9, CD28, or TNFRSF9, etc.), we found DHCR7 played roles both in inhibitors and activators of ICP in human cancers." (PMID 41198144, 2025). "In cancer, NFYC has been shown to modulate SREBF-driven pathways, linking it to the transcriptional control of metabolic genes such as DHCR7 and SLC38A2, both of which were also observed in our model." (PMID 40941703, 2025). "In summary, our findings establish DHCR7 as a key regulator of immune cell recruitment and function in the TEM across multiple cancer types." (PMID 41198144, 2025). "The expression of the TGF-β-regulated genes (DHCR7, FABP5, HMGCR, MVD, SQLE and STARD4) was further correlated with clinical features using cancer patient datasets." (PMID 39910665, 2025). "Notable examples—such as ANO1, BAG2, DHCR7, MMP2, and TRAM2 —align with prior studies linking these genes related to cancer proliferation or metastasis in multiple cancer types." (PMID 40361356, 2025). "Activated the caspase 2-S1P-SREBP1/2 pathway to up-regulate the expression of DHCR7 and FASN in cancer." (PMID 39906741, 2024). "Therefore, DHCR7 inhibition might alter ferroptosis sensitivity in proliferative cancer cells." (PMID 38472233, 2024). "Camptothecin amplified the effects seen in cancer (CHECK2, BCL-2 and IL8), but opposed them for CYP51A1, ITGA2, DHCR7 or HMGCS1." (PMID 28962550, 2017). "Therefore, we analyzed the potential connection of DHCR7 expression and immune cell infiltration in the TME of human cancers." (PMID 41198144, 2025). "Moreover, we created MSMO1 and DHCR7 knockdown cancer cells and discovered that MSMO1 or DHCR7 inhibition rescued the Az-induced increase in HLA-ABC." (PMID 38715057, 2024). "The 7‐dehydrocholesterol reductase (DHCR7) enzyme, a critical mediator of cholesterol biosynthesis, catalyzes the conversion of 7‐dehydrocholesterol (7‐DHC) to cholesterol, serving as a metabolic hub with pleiotropic implications in development, immunity, and cancer." (PMID 41198144, 2025). "Furthermore, 7-dehydrocholesterol reductase (DHCR7) has the function for the majority of cancer patients and can turn 7-DHC into non-toxic cholesterol outside the tumors." (PMID 36873996, 2023). "Additionally, the PPI network analysis revealed that DHCR7 may participate in G alpha signaling events, T cell receptor signaling pathway, and the CD8 TCR pathway in cancer." (PMID 36164611, 2022). "Additionally, in the final step of cholesterol biosynthesis, 7-dehydrocholesterol reductase (DHCR7) consumes its substrate 7-dehydrocholesterol (7-DHC), which shields lipids from autoxidation and subsequent fragmentation, potentially enabling cancer cells to evade ferroptosis." (PMID 39958433, 2025). "We therefore targeted DHCR7 and DHCR24, as both are non-essential cancer genes and contain PRDM9 motif at their promoters." (PMID 41397959, 2025).
tumor (25 papers, 2014 to 2026). "Then, we investigate the association between DHCR7 expression and tumor pathological staging as well as metastasis." (PMID 41198144, 2025). "High DHCR7 expression was significantly associated with tumor immune infiltration level, pathological M, and poor prognosis in BC." (PMID 38526324, 2024). "DHCR7 overexpression has been linked to increased cholesterol levels, which may promote tumor growth by: (a) Enhancing lipid raft formation, facilitating oncogenic signaling (e.g., PI3K/AKT, MAPK)." (PMID 41198144, 2025). "The expression levels of DHCR7 mRNA were significantly elevated in liver tumors compared with the non-tumor liver tissues." (PMID 40529212, 2025). "Among the modeled genes, DHCR7 was identified as significantly overexpressed in BLCA, strongly associated with prognosis, and implicated in regulating the tumor immune microenvironment." (PMID 40735323, 2025). "Inhibition of DHCR7 can improve the tumor immune microenvironment and enhance the efficacy of immunotherapy, suggesting that DHCR7 is a potential new target for LUAD immunotherapy." (PMID 41246332, 2025). "DHCR7 RNA and immunohistochemistry (IHC) analyses confirmed lower DHCR7 expression in shDHCR7-derived tumors than in control tumors during tumor development (O and EV2F)." (PMID 41249736, 2025). "Compared to the control group, the DHCR7 knockdown group (shDhcr7+IgG2a) showed significantly inhibited tumor growth, with markedly reduced tumor volume and weight." (PMID 41246332, 2025). "In comparison to the normal group, the expression levels of ACADM and ALDH1A1 were significantly down‐regulated in the tumor group, whereas the expression level of DHCR7 was significantly up‐regulated in the tumor group." (PMID 39716927, 2025). "To verify the potential function of DHCR7 in tumor tissue, we explored DHCR7 co‐expression networks using the Linked Omics database." (PMID 41198144, 2025). "The results demonstrated that DHCR7 expression levels vary significantly among different immune and molecular subtypes, suggesting its potential role in tumor immunomodulation." (PMID 41198144, 2025). "To further validate DHCR7’s biological function in tumor growth, we constructed a mouse xenograft tumor model." (PMID 41246332, 2025). "DHCR7 exhibited significant overexpression in most malignancies, correlating with advanced tumor stage (p < 0.05), metastatic progression, and reduced overall survival (HR = 1.34, 95% CI: 1.18–1.52)." (PMID 41198144, 2025). "DEN/HFD + EtOH-fed Dhcr7+/– mice developed fewer (↓2-fold) and smaller tumors than WT mice, as shown by reduced (↓3-fold) tumor burden." (PMID 40529212, 2025). "To test this, we conducted in vivo experiments and confirmed that Dhcr7 knockdown significantly suppressed tumor growth." (PMID 40735323, 2025). "Next, we examined the relationship between DHCR7 expression and clinical outcomes, including OS, tumor stages, and metastasis." (PMID 41198144, 2025). "Overall, our data indicate that targeted downregulation of DHCR7 expression in human HCC or inhibition of DHCR7 activity in the tumor microenvironment can ameliorate the development of MetALD and HCC." (PMID 40529212, 2025). "We resolve conflicting reports on DHCR7's dual roles in tumor progression (pro‐ vs. anti‐tumor effects) and immune regulation, elucidating its impact on immune checkpoint modulation and tumor microenvironment (TME) remodeling." (PMID 41198144, 2025). "Increased immunoreactivity for DHCR7 was detected in human HCC compared with non-tumor liver tissues." (PMID 40529212, 2025). "7-Dehydrocholesterol reductase (DHCR7) is a cholesterol epoxide hydrolase involved in fetal development and growth, tumor cell differentiation, and apoptosis." (PMID 38526324, 2024). "A xenograft model showed that DHCR7 knockdown inhibited the growth of subcutaneous tumors, whereas 27HC supplementation reversed the inhibitory effect of DHCR7 downregulation on tumor growth." (PMID 37891677, 2023).